INS (insulin)
Diseases named in the same sentence as INS in open-access papers (continued):
Sharing a sentence is not in itself a finding about the gene and the disease.
metabolic disorders (continued). "In the present study, T3, T4, insulin, GLP-1, GHRP, GH, SS and leptin were not significantly altered by the experimental diets, indicating that neither dietary protein level reduction nor fatty acid supplementation caused the metabolic disorders." (PMID 37239844, 2023). "There is some support for better glycemic control and insulin sensitivity in people with metabolic disorder when exercise is performed in the afternoon as opposed to the morning, but this work is still evolving as we discover more about circadian rhythms and metabolic gene regulation." (PMID 37606407, 2023). "GLP-1 acts on the pancreas to control insulin secretion and GLP-1-based therapies are now FDA (Food and Drug Administration)-approved for the treatment of T2D, however, patients with multiple metabolic diseases are likely to have a complicated EEC response to the available therapeutics." (PMID 37240181, 2023). "We thus speculated that Wnt+ adipocytes, driven by insulin/AKT signaling and functioning as a key regulator of beiging in mice, represent a population of beneficial adipocytes and hold the therapeutic potential for metabolic diseases." (PMID 35503096, 2022). "However, as there was a significant correlation between BMI and most cardiometabolic parameters (TC, TG, LDL-C, and insulin levels and HOMA-IR), it was confirmed that an increase in BMI could increase metabolic disease, as reported in previous studies." (PMID 35422707, 2022). "The metabolic disorder in PCOS might affect cord blood lipid and insulin." (PMID 33743611, 2021). "The metabolic disorder in PCOS might affect cord blood lipid and insulin and adulthood health." (PMID 33743611, 2021). "In addition, we found a beneficial effect of Gracilex® on insulin sensitization in a mouse model of HFD-induced metabolic disorder with a lack of some of the side effects described for the full agonist rosiglitazone on adipose differentiation." (PMID 34071972, 2021). "Additionally, the insulin, IR, and blood lipid were apparently reduced in rats fed with HFD and rhein, suggesting that rhein could improve metabolic disorder induced by HFD." (PMID 34516329, 2021). "Furthermore, intra-pancreatic fat deposition has a negative correlation with insulin secretion, and it promises to become a novel and more accurate biomarker for metabolic disorders." (PMID 32630574, 2020). "However, the greatest limitation of the CCl4-induced model is that the animals do not become obese or develop insulin resistant, which differs greatly from the pathophysiological characteristics in metabolic disorder induced NAFLD patients." (PMID 32508961, 2020). "Overall, ROCK1’s role in insulin signaling is complex, and the opposing effects of adipocyte-specific ROCK1 inhibition in healthy vs. pathological models, indicates an importance of basal ROCK1 activity to glucose homeostasis but also implicates its overactivity in metabolic disease pathologies." (PMID 33633690, 2020). "Here we show that Drosophila melanogaster (fruit fly) subject to obesogenic challenges exhibits metabolic disease phenotypes in skeletal muscle; sarcomere disorganization, mitochondrial deformation, upregulation of Phospho-AKT level, aberrant intramuscular lipid infiltration, and insulin resistance." (PMID 31221967, 2019). "One possible explanation is that the patients with T2DM employed in our research have not developed severe metabolic disorders, and a compensatory mechanism may have been triggered to retain normal insulin secretion." (PMID 31651303, 2019). "Results of a meta-analysis study including 763 participants with metabolic diseases from 16 randomized controlled trials revealed that folate supplementation significantly leads to decreases in insulin levels and HOMA-IR, but does not seem to affect FPG and HbA1c levels." (PMID 31807124, 2019).
metabolic disorders (continued). "However, group 2 had similar insulin levels, HOMA-IR, and MetS z-score with group 3, which suggest that a considerable number of NAFLD cases, although had severe metabolic disorder, would not be detected by the current diagnostic criterion." (PMID 29849623, 2018). "Importantly, exercise-induced glucose uptake was preserved in insulin-resistant skeletal muscle in which insulin failed to promote glucose uptake, emphasizing exercise as a key therapeutic intervention for metabolic diseases." (PMID 29209279, 2017). "It is suggested that glucose and lipid, not insulin might be inhibitory regulatory factor in muscle FNDC5 expression in metabolic disorders." (PMID 27354972, 2015). "Therefore, we assume that fenugreek activated firstly insulin sensitivity rather than insulin secretion in the relatively mild metabolic disorders we generated in rats through high-fat high-sucrose diets." (PMID 22188728, 2011). "Additionally, the insulin-sensitizing effects of the polyphenol, Resveratrol, through modulation of SIRT1/PGC-1α activity, have been highlighted as being beneficial in tackling aspects of metabolic disease." (PMID 21113404, 2010). "It is important to mention that in the preclinical stages of metabolic disorders, the fasting serum parameters of lipids, glucose, and insulin may not present alterations, so it is necessary to evaluate other more predictive or sensitive tests to establish differences between individuals." (PMID 36979696, 2023). "In the absence of Sx16, adipocytes still exhibit robust insulin-stimulated glucose transport but exhibit altered behavior in response to hyperinsulinemic conditions and changed metabolic profiles, a result with potentially important implications for the development of metabolic disease." (PMID 36467416, 2022). "Secondly, PCOS is a highly heterogeneous metabolic disorder, we did not further perform stratified analysis according to the metabolic index of these patients, such as fasting blood-glucose, fasting insulin, and serum lipid level, which might compromise pregnancy outcomes." (PMID 34248846, 2021). "Exercise can improve insulin sensitivity and thereby alter skeletal muscle glucose transport and maintain blood glucose homeostasis, especially for patients with metabolic disease, but may not always have the same effect in athletes due to excessive production of ROS during exercise training." (PMID 32899227, 2020). "Thus, insulin therapy can be beneficial even in a metabolic disorder of non-diabetic origin." (PMID 31089886, 2019). "In conclusion, our results suggested that CARD9 could have a new functional role in mediating energy metabolism, insulin resistance and inflammatory response in diet‐induced inflammation and metabolic disorders, which is likely independent of the innate immunity." (PMID 29575791, 2018). "Notably, certain pharmacological treatments, such as insulin, metformin, and DPP-4 inhibitors, may modify the biological response of diabetic patients during orthodontic treatment, in some cases attenuating the bone remodeling and inflammation that are characteristic of this metabolic disease." (PMID 40725571, 2025). "Accordingly, in our study, participants with higher fasting insulin and HOMA-IR levels exhibited lower skeletal muscle mitochondrial capacity, despite lacking a metabolic disease diagnosis." (PMID 35597962, 2022). "In a recent meta-analysis of 12 RCTs, Se supplementation did not improve the glycemic indices, such as FPG, insulin, and HOMA-IR in patients with metabolic disease." (PMID 35047136, 2021). "Therefore, the moderate decreases in post-prandial glucose and insulin, and the small decrease in post-prandial TAG, as a result of PA breaks in sitting, if confirmed in longer-term studies, may have implications for the prevention of metabolic disease, at least in comparison with only sitting." (PMID 31552570, 2020).
metabolic disorders (continued). "While the authors suggested the use of TZD during the transition period to improve insulin homeostasis and to prevent excessive body condition score losses, their effect on VAT, inflammatory status, and metabolic disease prevention was not addressed by the study, thus requiring further elucidation." (PMID 40599780, 2025). "This difference in peripheral insulin sensitivity after HCHFD between Asians and Caucasians might be the reason why non-obese Asians readily develop metabolic diseases." (PMID 37373776, 2023). "In fact we previously showed that new DM group detected with HbA1c has a more advanced metabolic disorder (higher BMI, waist, blood pressure, non-HDL-cholesterol, triglycerides, and insulin but lower HDL-cholesterol) than other new DM groups detected with FPG or 2-hPG." (PMID 26824043, 2016). "Hence, preservation of BAT, and insulin sensitivity in BAT and residual WAT, may at least partly explain why Ad-B2(−/−) mice do not develop the overt metabolic disease seen in PPARγ-FKO and IR-FKO mice." (PMID 29459250, 2018). "Although the isolated effective components of CLW have not been studied for their efficacy for treating metabolic diseases; the saponins, flavonoids and inulin in CLW may have a hypoglycemic effect by potentiating insulin secretion and improving insulin resistance." (PMID 29104217, 2017).
cancer (2,814 papers, 1978 to 2026). A tumor composed of atypical neoplastic, often pleomorphic cells that invade other tissues. "Subgroup analyses revealed that these associations were strongest for female-specific cancers in women with high baseline insulin levels." (PMID 41490246, 2026). "High insulin levels and chronic or persistent inflammation have been tied to increased risk of multiple cancer types, including PCa." (PMID 41546786, 2026). "These sex-specific patterns of fat distribution are associated with differences in insulin sensitivity, systemic inflammation, and potentially cancer susceptibility." (PMID 41490246, 2026). "Second, hormonal regulation plays a crucial role, particularly through weight management and dietary control, which help regulate hormone levels like estrogen and insulin that are linked to various cancers." (PMID 41554683, 2026). "The mechanism by which excess body weight increases cancer risk is possibly explained by insulin and IGF." (PMID 41376649, 2026). "We previously reported that high baseline insulin levels were associated with a greater treatment benefit of bariatric surgery for female-specific cancers." (PMID 41490246, 2026). "Contrastingly, a Western diet was associated with a higher cancer-specific mortality and overall mortality and high-inflammatory, hyperinsulinaemic, and insulin-resistant diets with increased recurrence." (PMID 40941553, 2025). "Affected kinases were significantly enriched in cancer-associated pathways, including insulin signaling, EGF–EGFR signaling, PI3K/AKT signaling, and the PD-L1/PD-1 immune checkpoint axis." (PMID 40832614, 2025). "Regular exercise decreases cancer risk by maintaining a healthy weight, regulating hormonal balance, particularly that between estrogen and insulin, and strengthening the immune system." (PMID 41514592, 2025). "The findings revealed that the use of GLP-1 receptor agonists was associated with a significant reduction in the risk of several cancers compared to insulin." (PMID 39777709, 2025). "Elevated blood glucose and insulin levels have been associated with worse outcomes in cancer patients, as hyperinsulinemia can promote tumor growth." (PMID 39944825, 2025). "Studies have suggested that certain glucose-lowering medications, including metformin, thiazolidinediones, insulin, and incretin-based therapies, are associated with decreased or increased risk of cancer." (PMID 40620564, 2025). "Key metabolic pathways are tightly linked to cancer development, including insulin signaling, insulin‐like growth factor‐1 (IGF‐1), and mTOR." (PMID 40777199, 2025). "• An inverse association exists for additional steps and lower insulin and leptin metabolic biomarkers in cancer survivors." (PMID 40783771, 2025). "Because of insulin’s potential role as a growth factor and its relationship with cancer risk, further studies with a larger number of insulin comparisons are needed to assess its impact on cancer risk relative to novel antidiabetic medications." (PMID 40290515, 2025). "Treatment with metformin, in contrast to other anti-diabetic drugs such as insulin and sulfonylurea, lowers the risk of cancer-associated mortality." (PMID 40374694, 2025). "One included study associated NODM incidence with weight loss, possibly due to cancer cachexia, which leads to systemic inflammation, proteolysis, and energy imbalance, which can impair insulin signalling." (PMID 41378064, 2025). "These molecules are also capable of modulating the activity of insulin, potentiating insulin resistance, which is a risk factor for most cancers." (PMID 41335382, 2025). "INS is a fundamental gene involved in glucose metabolism, and its dysregulation has been implicated in the pathogenesis of several cancers, including PDAC." (PMID 40699634, 2025). "Sulfonylureas and insulin have been linked to higher risks of certain cancers, particularly pancreatic cancer." (PMID 41300987, 2025).
cancer (continued). "Multiple studies have evaluated the cancer risk related to the administration of exogenous insulin and other diabetic medications." (PMID 41573197, 2025). "The use of insulin or insulin analogs has been reported in association with increased cancer risk compared to other antihyperglycemic drugs." (PMID 39976819, 2025). "Antidiabetic medications, notably metformin and insulin, have been shown to independently influence cancer risk." (PMID 40597094, 2025). "Commonly used in patients with diabetes to enhance insulin sensitivity, metformin has also been investigated for its potential effects on weight loss and cancer prevention." (PMID 40917133, 2025). "As many cancer cell types also overexpress the IR-A isoform, this variant is believed to provide malignant cells with a selective growth advantage when exposed to insulin, thus increasing the risk of cancer and its progression." (PMID 41018201, 2025). "These multifaceted effects of insulin and insulin resistance establish a strong mechanistic link between metabolic dysfunction and cancer risk." (PMID 41367907, 2025). "In both BC and other cancer contexts, elevated levels of insulin and IGF-1 have been implicated in tumorigenesis via activation of mitogenic and anti-apoptotic signaling pathways, such as Ras-MAPK and PI3K-Akt." (PMID 40731797, 2025). "Exercise has overlapping effects with CR in enhancing insulin sensitivity and decreasing inflammation, and has been associated with lower cancer incidence and reduced tumor growth." (PMID 40285503, 2025). "High glycemic load diets, which rapidly raise blood glucose and insulin levels, have been associated with increased cancer risk, while calorie restriction has been shown to reduce insulin and IGF-1 levels, potentially slowing tumor growth." (PMID 40428567, 2025). "Insulin was significantly positively associated with cancer grade and risk in both PCa+DM and PCa-DM groups." (PMID 41367482, 2025). "The overexpression of IR in breast tumors indicates that cancer cells are sensitive to elevated insulin levels and is associated with poor patient prognosis." (PMID 40353441, 2025). "It is well known that IR is associated with high insulin levels, so most studies tend to use this to explain the possible mechanism of TyG index as a cancer risk." (PMID 40756516, 2025). "Meanwhile, insulin-related traits are also thought to be strongly associated with cancer development." (PMID 40475768, 2025). "Conversely, the use of insulin and insulin secretagogues is associated with a heightened likelihood of this cancer’s emergence." (PMID 40168281, 2025). "Expanding on metformin, a reduced cancer risk with metformin has been described in a number of observational studies and in conjunction with reduced plasma insulin levels." (PMID 40277890, 2025). "In this setting, the metabolic hormones leptin, adiponectin, and insulin have been implicated as agonists of key tumor signaling pathways leading to cancer progression and patient mortality." (PMID 40444533, 2025). "It is suggested that the mechanisms that stimulate the mitogenic response of cancer cells to insulin and IGF-2 are associated with overexpression of INSR-A and and increased INSR-A/INSR-B ratio." (PMID 38392069, 2024). "The identified observational studies suggested that raw garlic intake had beneficial effects on prehypertension, handgrip strength, risk of different types of cancer, thickened cIMT, insulin homeostasis, and newly diagnosed NAFLD." (PMID 39279902, 2024). "At the same time, miR-375 is involved in insulin secretion and beta-cell function and is implicated in the proliferation of human cancer cells." (PMID 38831236, 2024). "The association among insulin, oral insulin secretagogues, and cancer risk was as a significant focus of research, particularly in the preceding years." (PMID 39595655, 2024).